TRIM33 (tripartite motif containing 33)
Diseases named in the same sentence as TRIM33 in open-access papers (continued):
Sharing a sentence is not in itself a finding about the gene and the disease.
pancreatic ductal adenocarcinoma (2 papers, 2017 to 2021). An infiltrating adenocarcinoma that arises from the epithelial cells of the pancreas. "For example, the expression of TRIM33 is downregulated in Pancreatic Ductal AdenoCarcinoma (PDAC), and it was shown that the inactivation of TRIM33 contributes to the development of cystic pancreatic tumors through the activation of Kras." (PMID 34298819, 2021).
squamous cell carcinoma (2 papers, 2020 to 2025). A carcinoma arising from squamous epithelial cells. "Conversely, increased YOD1 expression blocks ERK signaling by stabilizing TRIM33 activation, thereby inhibiting tumor invasion and lymph node metastasis in squamous cell carcinoma of the head and neck." (PMID 40274778, 2025).
triple-negative breast carcinoma (2 papers, 2016 to 2023). An invasive breast carcinoma which is negative for expression of estrogen receptor (ER), progesterone receptor (PR), and human epidermal growth factor receptor 2 (HER2). "For example, in triple-negative breast cancer, KAT6A promotes interactions between SMAD3 and TRIM24 by mediating SMAD3 acetylation and inhibiting interactions between SMAD3 and TRIM33, thereby promoting tumor progression by regulating the immune microenvironment." (PMID 36611207, 2023).
acute myeloid leukemia (1 paper, 2015). Acute myeloid leukemia (AML) is a group of neoplasms arising from precursor cells committed to the myeloid cell-line differentiation. "The majority of these factors had been identified in a prior screen that evaluated the requirement of chromatin regulators in MLL-AF9/NrasG12D acute myeloid leukemia (AML), however TRIM33 was identified here as a unique requirement in B-ALL." (PMID 25919951, 2015).
acute pancreatitis (1 paper, 2022). An acute inflammatory process that leads to necrosis of the pancreatic parenchyma. "The expression of Trim33 is increased during acute pancreatitis, but its molecular expression regulation mechanism is still unclear." (PMID 35169128, 2022). "Prior to this, the role of Trim33 in acute pancreatitis was unclear." (PMID 35169128, 2022).
adult-onset dermatomyositis (1 paper, 2021). "We investigate the accumulated microbial and autoantigen antibody repertoire in adult-onset dermatomyositis patients sero-positive for TIF1γ (TRIM33) autoantibodies." (PMID 33772100, 2021).
B-cell lymphomas (1 paper, 2021). "In addition, our result revealed the prognostic value of SEPT6_TRIM33 gene fusion in B-cell lymphomas." (PMID 34926267, 2021).
clear cell carcinoma (1 paper, 2020). "To explore the potential role of TRIM33 in clear cell carcinoma, we used the TCGA database to reveal the mRNA expression levels of TRIM33 in human ccRCC tissues and its clinical relevance." (PMID 32908919, 2020).
endometriosis (1 paper, 2024). The growth of functional endometrial tissue in anatomic sites outside the uterine body. "The results revealed that knockdown of TRIM33 significantly enhanced the protein expression of TGFBR1/p-SMAD2/α-SMA/FN1, suggesting that the reduced levels of TRIM33 protein in ectopic tissues may exacerbate endometriosis-associated fibrosis." (PMID 38735939, 2024). "However, the abnormal dysregulation of TRIM33 in endometriosis and its role in regulating endometriosis-associated fibrosis remain unclear." (PMID 38735939, 2024). "Finally, we uncovered the abnormal expression of E3 ubiquitin ligase TRIM33 in endometriotic tissues of endometriosis, along with its negative regulatory role in fibrosis of human endometrial stromal cells in vitro." (PMID 38735939, 2024). "It is important to note that, while our study provides compelling evidence supporting the crucial role of ubiquitination in endometriosis and the negative regulatory effect of TRIM33 on fibrosis, the specific regulatory mechanisms require further in-depth functional studies." (PMID 38735939, 2024). "This study, for the first time, provides a comprehensive understanding of endometriosis ubiquitination profiles and reveals the aberrant expression of the TRIM33 in endometriotic tissues, emphasizing their critical involvement in fibrosis pathogenesis and potential therapeutic targets." (PMID 38735939, 2024). "Overall, the present study, employing multi-omics approaches, presents a novel perspective for the first time on the ubiquitination profile and the aberrant expression of TRIM33 in endometriosis, highlighting their pivotal roles in fibrosis and their potential as future therapeutic targets." (PMID 38735939, 2024). "Consequently, we hypothesize that reduced TRIM33 expression in endometriotic tissues may contribute to the development of endometriosis fibrosis by enhancing TGFBR1/p-SMAD2/α-SMA/FN1 expression." (PMID 38735939, 2024).
esophageal cancer (1 paper, 2024). A primary or metastatic malignant neoplasm involving the esophagus. "The GSE9982 dataset from the public Gene Expression Omnibus (GEO) database showed that the expression of TRIM33 in the esophageal cancer cell line was higher than that in normal cells." (PMID 39389957, 2024).
fibrosis (1 paper, 2022). the formation of excess fibrous connective tissue in an organ or tissue in a reparative or reactive process. "To explore the contribution of TRIM33 to cardiac fibrosis and cardiac function in vivo, we injected the TRIM33 overexpression adeno-associated virus 9 (AAV9-TRIM33)-treated mice and the sham-treated mice with Ang II (15 mg/kg/day subcutaneously for 28 days)." (PMID 35333698, 2022).
latent infection (1 paper, 2023). "TRIM33 phosphorylations were detected on T781, S787 and S789, and these SUMO/phospho peptides were only detected in the reactivated EBV samples and not in latent infection." (PMID 37410772, 2023).
lymphoid leukemia (1 paper, 2015). A malignant lymphocytic neoplasm of B-cell or T-cell lineage involving primarily the bone marrow and the peripheral blood. "Our ChIP-seq analysis of TRIM33 in myeloid, B lymphoid, and T lymphoid leukemias suggests that other TFs are also likely to recruit TRIM33, such as TCF3/E2A." (PMID 25919951, 2015).
medullary thyroid carcinoma (1 paper, 2023). "Exposure of LUAD-0002AS1 (NSCLC, KIF5B–RET), ECLC5B (NSCLC, tripartite motif-containing 33 (TRIM33)–RET) and TT cells (medullary thyroid carcinoma, RETC634W) to vepafestinib resulted in efficient downregulation of RET phosphorylation at Y905 and Y1062 and downstream effectors." (PMID 37743366, 2023).
myeloid leukemia (1 paper, 2015). A clonal proliferation of myeloid cells and their precursors in the bone marrow, peripheral blood, and spleen. "While both B lymphoid and myeloid leukemia cells harbor PU.1 and TRIM33 at the Bim –117 region, it is important to note that knockdown of TRIM33 in AML does not result in apoptosis or Bim upregulation." (PMID 25919951, 2015).
Myocardial fibrosis (1 paper, 2022). "In the present study, we clarified that TRIM33 attenuated Ang II–induced myocardial fibrosis in vivo and in vitro by mediating TGF-β1/Smad3/4 signaling and that the effect of TRIM33 was regulated by HSPB5." (PMID 35333698, 2022). "In this study, we hypothesized that TRIM33 participates in mediating myocardial fibrosis induced by Ang II." (PMID 35333698, 2022). "The underlying molecular mechanism of the role of TRIM33 in Ang II–induced myocardial fibrosis is not fully understood." (PMID 35333698, 2022). "Thus, in addition to eliminating Ang II–induced CF proliferation and ECM synthesis, TRIM33 overexpression protects against Ang II–induced heart size, cardiac dysfunction and myocardial fibrosis in vivo." (PMID 35333698, 2022). "Moreover, these biological functions of TRIM33 in blocking myocardial fibrosis could be reversed by HSBP5." (PMID 35333698, 2022). "In this study, we found that the expression of TRIM33 was upregulated in Ang II–induced fibrotic myocardium and CFs, but there was no significant change in cardiomyocytes, indicating that Trim33 may be a functional therapeutic target in the occurrence and development of myocardial fibrosis." (PMID 35333698, 2022). "We proved that TRIM33, which is mediated by HSPB5, could protect against myocardial fibrosis through TGF-β1-Smad3/4 signaling." (PMID 35333698, 2022). "However, the regulatory role of TRIM33 and HSPB5 in myocardial fibrosis is still unclear." (PMID 35333698, 2022).
pancreatitis (1 paper, 2022). Inflammation of the pancreas. "Functional analysis revealed that Trim33 is involved in the degradation of ubiquitinated proteins in pancreatitis." (PMID 35169128, 2022).
papillary thyroid cancers (1 paper, 2012). "RET fusions (involving CCDC6, PRKAR1A, NCOA4 (ELE1), GOLGA5, TRIM24 (HTIF1), TRIM33 (RFG7), and KTN1 and ERC1 (ELKS)) are found in papillary thyroid cancers." (PMID 22928112, 2012).
peritonitis (1 paper, 2017). Inflammation of the peritoneum (tissue that lines the abdominal wall and covers most of the organs in the abdomen). "After thioglycollate-induced peritonitis, the number of SPM in Control and Trim33−/− mice was similar and these SPM were all deleted for Trim33." (PMID 27974684, 2017). "After thioglycollate-induced peritonitis, the number of SPM was three-fold reduced in MxCre/Trim33−/− mice compared to MxCre/Control mice and these SPM had a complete deletion of Trim33." (PMID 27974684, 2017).
prostate tumor (1 paper, 2024). "TRIM33 also drives prostate tumor growth by stabilizing Skp2-mediated androgen receptor degradation." (PMID 39389957, 2024).
psoriasis (1 paper, 2024). An autoimmune condition characterized by red, well-delineated plaques with silvery scales that are usually on the extensor surfaces and scalp. "Trim33 promoted ANXA2’s interaction with p50/p65 subunits of NF-κB by catalyzing lysine 63 (K63)-linked ubiquitination of Annexin A2 (Anxa2) to stir inflammation response in psoriasis." (PMID 38688909, 2024).
renal carcinoma (1 paper, 2020). A carcinoma arising from the epithelium of the renal parenchyma or the renal pelvis. "In order to select the renal cancer cell lines suitable for this study, we used qRT-PCR and western blotting to determine the expression of TRIM33 in HK-2 and the three renal cancer cell lines." (PMID 32908919, 2020). "To investigate whether TRIM33 overexpression affects the proliferation of renal cancer cell lines, we used the CCK-8 assay and performed colony formation experiments to observe the changes between the overexpression group and the control group." (PMID 32908919, 2020). "However, the addition of Wnt agonist 1 can effectively eliminate the inhibitory effect on the migration and invasion of the two renal cancer cell lines due to the overexpression of TRIM33." (PMID 32908919, 2020). "In vivo, the growth rate of TRIM33-overexpressing renal cancer cells was significantly inhibited." (PMID 32908919, 2020). "Western blotting was used to explore the potential mechanism of TRIM33 in renal cancer cells." (PMID 32908919, 2020). "We found that the proliferation of renal cancer cell lines overexpressing TRIM33 was decreased." (PMID 32908919, 2020). "To investigate whether TRIM33 overexpression in renal cancer cell lines can inhibit tumor development in vivo, we conducted experiments in mice with subcutaneous tumors." (PMID 32908919, 2020). "Finally, in the mouse xenograft model, ACHN renal cancer cells overexpressing TRIM33 produced significantly smaller tumors in mice." (PMID 32908919, 2020). "In vitro, TRIM33 overexpression inhibited the proliferation, colony formation, migration, invasion, and EMT ability of renal cancer cells." (PMID 32908919, 2020).
sarcoma (1 paper, 2023). A usually aggressive malignant neoplasm of the soft tissue or bone. "Here, we describe a case of a sarcoma, associated with a RET::TRIM33-fusion gene with an exceptional response to a neoadjuvant therapy with the selective RET inhibitor selpercatinib." (PMID 36469155, 2023). "We report an highly effective neoadjuvant and adjuvant treatment of a patient with a RET::TRIM33-fusion sarcoma with the selective RET inhibitor selpercatinib." (PMID 36469155, 2023).
uterine corpus endometrial carcinoma (1 paper, 2021). A endometrial carcinoma (disease) that involves the body of uterus. "Elevated expression of TRIM33 is significantly associated with worse survival for Uterine Corpus Endometrial Carcinoma (UCEC) patients and with better survival for COAD and KIRC patients." (PMID 33810347, 2021).
cancer (130 papers, 2008 to 2025). A tumor composed of atypical neoplastic, often pleomorphic cells that invade other tissues. "Although the results of an immunohistochemical study did not reveal a significant correlation between muscular expression of TIF1γ and cancer risk in DM, other data suggested an association between somatic mutations of the TRIM33 gene and paraneoplastic DM." (PMID 38929849, 2024). "Low expression or loss of TRIM33 is observed in several cancer types, and although its function is cell-type specific, TRIM33 is largely considered as a tumour suppressor." (PMID 38627415, 2024). "Its dual role as a tumor suppressor or inducer has been described in numerous cancer studies and somatic mutations of the TRIM33 gene have been reported in patients with paraneoplastic DM." (PMID 38929849, 2024). "According to GeneCards.org database, ten ncRNA genes aligning with TRIM33 nucleotide sequence have known associations with human disease, including cancer." (PMID 38929849, 2024). "To date, there are no clear associations between the expression of a specific splice variant of the TRIM33 gene and the risk of cancer or DM." (PMID 38929849, 2024). "These eight transcripts were linked to the following cancer‐related genes: TRIM33, USP6, PRDM16, SETD1B, MLLT3, KEAP1, CHD2, and DCAF12L2." (PMID 32821278, 2020). "In fact, the cancer cell's dependency on the protein is due to TRIM33 associating with just a single binding site." (PMID 25919951, 2015). "For example, ABI1 and TRIM33 were both known cancer genes and were included in the CGC list, but their mutation patterns in UCEC have been rarely reported, even in the most recent comprehensive studies." (PMID 25348067, 2014). "In conclusion, the results of this in silico analysis show sequence complementarity and predict interactions between the TRIM33 gene and human ncRNAs dysregulated in cancer and DM." (PMID 38929849, 2024). "Our work highlights the rationale for further investigation of the role of TRIM33 in the progression of cancers characterized by increased levels of ER expression." (PMID 38473207, 2024). "Link of TRIM33 to cancer has also been studied and was shown to either act as a tumor suppressor or as a tumor promoter, depending on the cell type examined." (PMID 38342435, 2024). "The sum of these events can lead to the emergence of TRIM33 isoforms, to an imbalance in the T cell subpopulation and to the acceleration of cancer development or the occurrence of autoimmune phenomena." (PMID 38929849, 2024). "TRIM33 offers a novel target for inhibiting estrogen-induced cancer cell growth, particularly in cases of endocrine resistance driven by ER (ESR1) gene amplification or overexpression." (PMID 38473207, 2024). "NcRNA genes whose polymorphic variants have been associated with cancer risk included NNT-AS1, LINC01116, and SILC1, which matched the TRIM33 gene with a score of 903 (%ID 91.8%), 577 (%ID 98.7%), and 466 (%ID 97%), respectively." (PMID 38929849, 2024). "The expression of TRIM33 can be used as an early biomarker to evaluate the risk of malignant transformation and as an intervention target for ESCC, providing an option for cancer treatment targeting glucose metabolism." (PMID 39389957, 2024). "Across several cancer types, TRIM33 has been shown to have varied roles as a tumor suppressor or oncogene, suggesting a context-dependent function of TRIM33." (PMID 38473207, 2024). "This further indicates that TRIM33 has a unique cell-type, background, and functional specificity, even in the same cancer type." (PMID 39389957, 2024). "In cancer, TRIM33 was predominantly identified as a tumor suppressor, and low TRIM33 expression correlated with enhanced genomic instability, resulting in cancer progression." (PMID 36674511, 2023).